WDR36 (WD repeat domain 36)
Description:
Part of the small subunit (SSU) processome, first precursor of the small eukaryotic ribosomal subunit. During the assembly of the SSU processome in the nucleolus, many ribosome biogenesis factors, an RNA chaperone and ribosomal proteins associate with the nascent pre-rRNA and work in concert to generate RNA folding, modifications, rearrangements and cleavage as well as targeted degradation of pre-ribosomal RNA by the RNA exosome. Involved in the nucleolar processing of SSU 18S rRNA. Involved in T-cell activation and highly coregulated with IL2.
Synonyms: TA-WDRP; UTP21; GLC1G; TAWDRP
Target class: Reader; Epigenetic regulator; Methyl-lysine/arginine binding protein; WDR domain
Gene: Protein-coding gene on chromosome 5 (111,092,303 to 111,130,502, forward strand). Ensembl gene ENSG00000134987.
Subcellular location: Nucleus, nucleolus
Subcellular location (Human Protein Atlas): Nucleoli
Pathways (Reactome):
Metabolism of RNA: Major pathway of rRNA processing in the nucleolus and cytosol; rRNA modification in the nucleus and cytosol
Genetic constraint (gnomAD): Loss-of-function variants: 53 observed, 94.35 expected, observed/expected ratio (o/e) 0.56, 90% interval 0.45 to 0.71. The upper end of that interval is the gene's LOEUF score, 0.71, which puts it in group 2 of 6, group 1 being the genes least tolerant of losing a copy. Missense variants: 1,073 observed, 996.49 expected, observed/expected ratio (o/e) 1.08, 90% interval 1.02 to 1.13. Synonymous variants: 370 observed, 344 expected, observed/expected ratio (o/e) 1.08, 90% interval 0.99 to 1.17.
Homologues: Orthologues: chimpanzee WDR36 (99% identical), macaque WDR36 (99% identical), rabbit WDR36 (94% identical), dog WDR36 (92% identical), pig WDR36 (91% identical), guinea pig WDR36 (91% identical), rat Wdr36 (89% identical), mouse Wdr36 (89% identical), tropical clawed frog wdr36 (68% identical), zebrafish wdr36 (65% identical), Drosophila melanogaster CG9799 (39% identical), Caenorhabditis elegans Y45F10D.7 (30% identical). Paralogues in human: PRPF19 (12% identical).
Diseases named in the same sentence as WDR36 in open-access papers:
WDR36 is named in the same sentence as 23 diseases in open-access papers, as found by Europe PMC text mining. Sharing a sentence is not in itself a finding about the gene and the disease. The quoted sentences say what the papers report.
glaucoma (43 papers, 2007 to 2025). Increased pressure in the eyeball due to obstruction of the outflow of aqueous humor. "Whereas several studies have indicated that genetic variants in WDR36 gene are contributing risk factors for glaucoma progression and severity, recent clinical trials and meta-analyses have suggested a lack of effect." (PMID 38241218, 2024). "WDR36 (WD40-repeat 36) gene variants were first reported to cause primary open-angle glaucoma (POAG) in 2005." (PMID 39456800, 2024). "Through linkage analysis, 23 loci and four genes (MYOC/TIGR, CYP1B1, OPTN, and WDR36) had already been associated with glaucoma in the past years." (PMID 38241218, 2024). "Approximately 10% of glaucoma cases are the result of genetic variants of myocilin, optineurin or WDR36, and 20% of primary open-angle glaucoma patients are involved in an even wider genetic link." (PMID 30371760, 2018). "Three different mutant forms of Utp21 analogous to glaucoma-associated WDR36 mutations exhibit reduced levels in yeast cells expressing mutations in Hsp90 or associated chaperones, suggesting that Hsp90 and co-chaperones buffer the effects of those mutations." (PMID 24647762, 2014). "Mutation of zebrafish Bap28, the ortholog of human UTP10, results in excess apoptosis primarily in the central nervous system, while mutation in WDR36/UTP21, a modifier protein to human primary open angle glaucoma (POAG), results in mouse embryonic lethality." (PMID 24497835, 2014). "Mutations in the human homolog of UTP21, WDR36, have been associated with adult-onset primary open-angle glaucoma, a leading cause of blindness worldwide." (PMID 24647762, 2014). "PGP-15 had a glaucoma-associated high-penetrance variant in the gene WDR36 (A449T), and PGP-88 had a rare variant (N286T) in the glaucoma-associated gene PCMTD1." (PMID 25188385, 2014). "A subset of UTP21 mutations analogous to glaucoma-associated mutations in WDR36 also exhibited enhanced growth defects when combined with a deletion in STI1, suggesting Sti1 has a general role in regulating Utp21 function." (PMID 24647762, 2014). "The contribution of WDR36 variation to glaucoma pathogenesis is controversial because many of the rare non-synonymous WDR36 variants sequenced in patients are also present in normal control individuals." (PMID 21850170, 2011). "We previously discovered that variants in yeast U3 protein 21 (UTP21), homologous to those found in WDR36 in glaucoma patients, alter cell proliferation in strains deficient for the co-chaperone protein stress-induced-phosphoprotein 1 (Sti1p)." (PMID 21850170, 2011). "Synthetic mutations of UTP21 that are homologous to glaucoma-associated variants of human WDR36 affect processing of the pre-rRNA transcript in yeast that are deficient for STI1." (PMID 21850170, 2011). "In yeast models, certain Utp21 variants homologous to glaucoma-associated variants in human WDR36 cause functional defects in a stress-induced-phosphoprotein 1 (Sti1) mutant background, arguing that WDR36 contributes to polygenic forms of glaucoma." (PMID 19347049, 2009). "No sequence variations in the coding exons or splicing junctions of WDR36 were found to be associated with glaucoma." (PMID 17563728, 2007). "Similarly, contradictory results are reported for the association of pathogenic variants in the WDR36 gene with glaucoma." (PMID 38241218, 2024). "However, in at least one study, the presence of WDR36 variants was associated with more severe disease, suggesting it is a glaucoma-modifier gene." (PMID 24647762, 2014). "However, genes consistently implicated so far (MYOC, OPTN, WDR36) are relevant only in a limited number of families and explain a small proportion of the glaucoma cases in the general population." (PMID 22570627, 2012).
glaucoma (continued). "Four genes, trabecular meshwork inducible glucocorticoid response (MYOC/TIGR), human dioxin-inducible cytochrome P450 (CYP1B1), optineurin (OPTN), and WD repeat domain 36 (WDR36), have been identified as glaucoma-causing genes, with MYOC being the first identified POAG gene." (PMID 21655360, 2011). "Because juvenile-onset glaucoma, which is associated with single-gene mutations, shares clinical and histopathologic features with adult-onset glaucoma, monogenic glaucoma genes like MYOC and WDR36 may be associated with complex glaucoma." (PMID 18432317, 2008). "Mutations in the CYP1B1, MYOC, OPTN, and WDR36 genes result in glaucoma." (PMID 17563717, 2007). "Three genes associated with glaucoma have been identified within these loci: myocilin/trabecular meshwork glucocorticoid response (TIGR) (GLC1A), optineurin (GLC1E), and WDR36 (GLC1G)." (PMID 39456800, 2024). "Three genes associated with glaucoma have been identified within specific loci, including myocilin/TIGR (GLC1A), optineurin (GLC1E), and WDR36 (GLC1G)." (PMID 39456800, 2024). "Those rare variants are located in CYP1B1, SIX6, CARD10, MFN1, OPTC, OPTN, and WDR36 glaucoma-related genes." (PMID 38241218, 2024). "Another gene correlated with glaucoma pathogenesis constitutes WDR36, which contains several iterations of the WD40 repeat motif (WD40-repeat 36)." (PMID 32545285, 2020). "Previous genome-wide association studies identified over 10 genes associated with primary open-angle glaucoma, including myocilin (MYOC), optineurin (OPTN) and WD repeat domain 36 (WDR36)." (PMID 32953253, 2020). "Mutations in WDR36, the human UTP21 gene, have been associated with primary open angle glaucoma, a leading cause of blindness." (PMID 24466140, 2014). "Myocilin (MYOC), Optineurin (OPTN), WD repeat domain 36 (WDR36) and CYP1B1 are well-established causative genes for various forms of glaucoma." (PMID 25054348, 2014). "Contrary to other known genes causing PCG (CYP1B1) or POAG (MYOC, OPTN, and WDR36), one can easily consider a plausible cellular and molecular basis for association between LTBP2 and the glaucoma phenotype." (PMID 23401661, 2013). "Four genes, including trabecular meshwork inducible glucocorticoid response (MYOC), human dioxin-inducible cytochrome P450 (CYP1B1), optineurin (OPTN), and WD repeat domain 36 (WDR36), have been identified as glaucoma-associated genes." (PMID 22876119, 2012). "To date, about 23 loci have been linked to different types of glaucoma, and four genes, myocilin (MYOC), optineurin (OPTN), cytochrome P450 1B1 (CYP1B1), and WD repeat domain 36 (WDR36), have been identified as glaucoma causing genes." (PMID 19668597, 2009). "The function of WDR36 and its role in the normal ocular physiology and glaucoma is still unclear, but WDR36 has been identified as being involved in T cell activation." (PMID 17563723, 2007). "Other studies have raised the possibility that the 5q22 region might harbour common genetic factors regulating glaucoma risk since the WDR36 gene is located in that area (5q22.1, locus GLC1G)." (PMID 34348663, 2021). "GAS7 may interact with other genes implicated in glaucoma pathogenesis such as MYOC, OPTN, WDR36, CAV1, nitric oxide synthase 2 (NOS2), forkhead box C1 (FOXC1), apolipoprotein E (APOE), amyloid precursor protein (APP), and clusterin (CLU)." (PMID 32545285, 2020). "Although more than 15 loci have been identified for glaucoma till date, only five genes have been identified with the causative mutations which include the following: MYOC/TIGR, OPTN, ASB10, WDR36, and EFEMP1." (PMID 28707069, 2018). "Mutations in the human homolog of UTP21, WDR36, have been associated with glaucoma." (PMID 24647762, 2014). "Among the five known glaucoma-causing genes– MYOC (myocilin), CYP1B1 (cytochrome P450, family 1, subfamily B, polypeptide 1), OPTN (optineurin), WDR36 (WDR36), and LTBP2 (latent transforming growth factor beta binding protein 2)–all except WDR36 were identified in three of the studies." (PMID 22312193, 2012).
glaucoma (continued). "The second was identified in individuals without glaucoma in West Africa and Mongolia and was located in the 5q22-23 region, which had already been implicated in glaucoma (WDR36 gene and GLC1M locus)." (PMID 22570627, 2012). "However, there are conflicting reports regarding the involvement of WDR36 in the pathogenesis of primary open-angle glaucoma (POAG)." (PMID 22025897, 2011). "Recent studies suggested that WDR36 defects may contribute to the glaucomatous disease process as a glaucoma modifier gene." (PMID 19145250, 2009). "Although WDR36 has been shown to function in 18S rRNA processing and transcription activation, the exact role of WDR36 in glaucoma remains unclear." (PMID 19347049, 2009). "The aim of the current study was a similar evaluation of PEG patients for the presence of mitochondrial abnormalities and nuclear gene mutations associated with various types of glaucoma (MYOC, OPTN, WDR36, and CYP1B1) and certain inherited optic neuropathies (OPA1 and OPA3)." (PMID 18246027, 2008). "Likewise in glaucoma, common pathogenic mutations had been found in unaffected individuals suggesting an incomplete penetrance, such as the MYOC p.Thr377Met, OPTN p.Glu50Lys, and WDR36 p.Asp658Gly." (PMID 22815630, 2012). "Adult-onset chronic open angle glaucoma, the most common type of glaucoma, has also been reported to show strong evidence for genetic heterogeneity, and at least 11 genetic loci, along with 3 genes (myocilin, optineurin, and WD repeat domain 36 gene [WDR36]), have been identified." (PMID 21921986, 2011). "myocilin (MYOC), optineurin (OPTN), WDR36 and neurotrophin-4 (NTF4) in primary open angle glaucoma (POAG) and CYP1B1 and LTBP2 in congenital and developmental glaucomas." (PMID 21150032, 2011). "Disease-associated sequence variants in three genes, myocilin (MYOC, GLC1A), optineurin (OPTN,GLC1E), and WD repeat domain 36 (WDR36, GLC1G), have been described in POAG and other types of glaucoma." (PMID 19096531, 2008). "MYOC, OPTN, WDR36, and CYP1B1 have all been identified in a relatively small percentage of patients with various types of glaucoma, and it remains possible that these genes are abnormal with a small percentage of PEG patients." (PMID 18246027, 2008). "Furthermore, disease alleles were observed for other autosomal dominantly inherited degenerative diseases of sensory function, including retinitis pigmentosa (SEMA4A, RP1), deafness (MYO1A), glaucoma (CYP1B1, OPTN, WDR36), and keratoconus (VSX1)." (PMID 25333069, 2014). "Genes that interact with WDR36, such as STI1, are excellent candidates for glaucoma modifier loci." (PMID 21850170, 2011). "WD repeat domain 36 (WDR36), neurotrophin 4 (NTF4), ankyrin repeat and SOCS box-containing 10 (ASB10), and TANK-binding kinase 1 (TBK1) are other genes that have also been reported to be glaucoma-causing genes, but are controversial or have not yet been widely replicated." (PMID 22509100, 2012). "The expression levels of hub genes were significantly correlated with the expression levels of multiple glaucoma-related genes, among which HSPA8 was significantly negatively correlated with CYP1B1 (Pearson r = − 0.48) and RPL15 was significantly positively correlated with WDR36 (Pearson r = 0.58)." (PMID 37968618, 2023).
primary open-angle glaucoma (11 papers, 2008 to 2024). "Mutations in WDR36, also a member of the WD repeat protein family, have been associated with adult-onset primary open-angle glaucoma (POAG)." (PMID 18776954, 2008). "Mutations in the human homolog of UTP21, WDR36, have been associated with adult-onset primary open-angle glaucoma (POAG), a leading cause of blindness worldwide." (PMID 24647762, 2014).
asthma (6 papers, 2012 to 2022). "While some of the discovered genes were linked to asthma pathophysiology, the role of other genes such as WDR36 and CLEC16A is still uncertain and needs further investigation." (PMID 36294997, 2022). "These were in loci previously associated with asthma exacerbations (GSDMB, RAD50, HLA‐DQB1, ADAM33, VDR, and CDHR3) or moderate‐to‐severe asthma (IKZF3, TSLP, MUC5AC, C11orf30, SMAD3, and WDR36)." (PMID 35754128, 2022). "At 5q22.1, TSLP and WDR36 were proposed to be candidate genes for asthma in Caucasian population." (PMID 22545103, 2012). "More recently, a genome-wide association study in a Japanese population-based cohort of adult asthma utilizing fine mapping analysis of the region on chromosome 5q22 using 13 tag SNPs showed that rs1837253 represented an associated LD block spanning 88 kb that included two genes, TSLP and WDR36." (PMID 22973903, 2012).
low tension glaucoma (4 papers, 2007 to 2021). A form of glaucoma in which chronic optic nerve damage and loss of vision normally attributable to buildup of intraocular pressure occurs despite prevailing conditions of normal intraocular pressure. "The findings in the current study indicate that WDR36 gene variants may be only rare causes of normal tension glaucoma in the German population." (PMID 17563723, 2007). "WDR36 is responsible for adult-onset and low-tension glaucoma and accounts for 5%–17% of adult-onset POAG cases." (PMID 18432317, 2008).
adult onset asthma (1 paper, 2020). "A singular GWAS study of a Japanese adult-onset asthma population showed that SNPs of HLA-, thymic stromal lymphopoietin-WD repeat domain 36 (TSLP-WDR36)-, and ubiquitin specific peptidase 38-GRB2 associated binding protein 1 (USP38-GAB1) loci are associated with adult-onset asthma." (PMID 32292784, 2020).
bladder carcinoma (1 paper, 2021). "Three of the novel missense mutational cancer genes were mutated at >1% in their respective TCGA cancer types: ATP10D (9.4% in melanoma), SVIL (3.2% in ovarian carcinoma) and WDR36 (3.2% in bladder carcinoma)." (PMID 34313788, 2021).
colon adenocarcinoma (1 paper, 2022). "Among the genes, the authors reported WDR36 (rs7705304) as a prognostic germline variant in colon adenocarcinoma." (PMID 36552033, 2022).
diabetes mellitus (1 paper, 2015). A metabolic disorder characterized by abnormally high blood sugar levels due to diminished production of insulin or insulin resistance/desensitization. "However, SNP rs12522383 in WDR36 was associated with diabetes mellitus (p = 0.00008)." (PMID 25669751, 2015).
leukemia (1 paper, 2022). A malignant (clonal) hematologic disorder, involving hematopoietic stem cells and characterized by the presence of primitive or atypical myeloid or lymphoid cells in the bone marrow and the blood. "These involve genes which are known to be leukemia drivers (such as FAT1, NOTCH1, PHF6, FLT3), and can activate signaling pathways that push the cells to multiply faster, as well as genes involved in ribosome biogenesis or translational control (such as WDR36 and LTV1)." (PMID 36482893, 2022).
WDR36 also shares sentences with these, for which no sentence is quoted: Blindness (2 papers); Adult onset (1); Allergy (1); cancer (1); deafness (1); degenerative diseases (1); eczema (1); hay fever (1); keratoconus (1); melanoma (1); nail-patella syndrome (1); ovarian carcinoma (1); pancreatic cancer (1); retinitis pigmentosa (1).